EGFR (epidermal growth factor receptor)
Diseases named in the same sentence as EGFR in open-access papers (continued):
Sharing a sentence is not in itself a finding about the gene and the disease.
squamous cell carcinoma (continued). "The EGFR in A431 cells, the squamous cell carcinoma cell lines, are glycosylated by A antigen, as well as Lewis Y antigen, another product of FUT1 that is mostly expressed in cancer cells, and these sugar structures influence the binding of the EGF to its binding site on the receptor." (PMID 39420441, 2024). "A similar effect is found in multicellular aggregates formed by cultured HSC-2 squamous carcinoma cells, where EGFR is recruited to sites of E-cadherin-mediated adhesion between cells, forms a complex with E-cadherins, is activated in a ligand-independent manner, and induces ERK1/2 phosphorylation." (PMID 39594667, 2024). "Finally, in vivo US-mediated delivery of siRNA against epidermal growth factor receptor (EGFR) was investigated in a murine model of squamous cell carcinoma (SCC)." (PMID 38577322, 2024). "Remarkably, a total of 135 (9.3%) non‐adenocarcinoma tumors harbored EGFR mutations, including 10 with squamous cell carcinoma, two with mixed histology, and 123 with carcinoma not otherwise specified, that were tested given the clinical indication." (PMID 38456253, 2024). "However, overexpression of Desmoglein-2 in human squamous carcinoma A431 cells enhances EGFR activation and increases cell proliferation in a c-Src- and EGFR-dependent manner." (PMID 39594667, 2024). "Additionally, specific subtypes are characterized by different mutations: adenocarcinoma typically exhibits changes in the EGFR and ALK genes, while squamous cell carcinoma is associated with alterations in the PIK3CA and FGFR1 genes." (PMID 38339175, 2024). "In addition, it has been observed that EGFR inhibition in canine squamous cell carcinomas reduces COX-2 expression, demonstrating the interdependence of these pathways." (PMID 38248333, 2024). "Furthermore, the targeting of both EGFR and mTOR by a combination of erlotinib and temsirolimus, respectively, has been effective in EGFR-resistant squamous cell carcinoma (SCC) [1519]." (PMID 39273409, 2024). "In squamous cell carcinoma (SCC), CD109 is essential for tumor progression and is associated with increased EGFR expression/stabilization, and enhanced EGFR/Akt signaling, which are crucial for maintaining epithelial morphology and cellular stemness, as shown by us and others." (PMID 39990858, 2024). "The near ubiquitous overexpression of epidermal growth factor receptor (EGFR)—with estimates of > 90 % overexpression in squamous cell carcinoma (SCC) —has led to the development of numerous molecular therapeutic agents, which have been subsequently leveraged for fluorescence imaging." (PMID 34651290, 2023). "The indirect cost per capita was $1670 in non-squamous carcinoma pathological type, $1709 in metastatic clinical stage, $2404 in disease progression, $2080 in immunotherapy, and $1491 in the subgroup with no EGFR mutation and ALK rearrangement." (PMID 36056953, 2023). "Of note, a total of 19 non-adenocarcinoma patients harbored EGFR mutations, including 12 with squamous cell carcinoma, 4 with carcinoma not otherwise specified, 2 with mixed histology, and 1 with sarcomatoid carcinoma." (PMID 35980949, 2022). "Similarly, squamous cell carcinoma, KRAS mutations, and EGFR L858R mutation were more commonly found in males than females." (PMID 35061839, 2022). "Exosomes isolated from patients with EGFR mutation showed significant increased activity of pro-MMP-9 and MMP-9 compared to exosomes isolated from serum from wild-type adenocarcinoma (ADK WT), squamous cell carcinoma, or healthy donors." (PMID 35954442, 2022). "In NSCLC, female gender and adenocarcinoma may indicate higher chance of EGFR exon 19 deletion or L858R, and smoking history may indicate squamous cell carcinoma and EGFR L858R." (PMID 35061839, 2022). "EGFR was present in 85% of squamous cell carcinoma cases, labeling 15–85% of cells." (PMID 35956111, 2022).
squamous cell carcinoma (continued). "Furthermore, we also observed that smokers were more frequently to have squamous cell carcinoma and KRAS mutations, and less frequently to have EGFR L858R." (PMID 35061839, 2022). "The findings obtained in this investigation indirectly concur with the observations made with the intravenous application of cetuximab in patients undergoing therapy of metastatic colorectal cancer or advanced squamous cell carcinoma of head and neck with EGFR expression." (PMID 35794227, 2022). "Notably, analyses using microarray datasets in Oncomine reveal an elevated Blimp-1 mRNA expression in samples of tongue squamous cell carcinoma, correlating to the high frequencies of EGFR overexpression in squamous cell carcinomas." (PMID 35185556, 2022). "Finally, an EGFR immunohistochemical response was present in all poorly differentiated squamous cell carcinoma cases, moderately or strongly staining 45–85% of the tumor cells." (PMID 35956111, 2022). "The epidermoid carcinoma cell line A431 had high EGFR overexpression (>300,000 molecules per cell)." (PMID 35035479, 2022). "For example, a 5-fold increase in the tumor accumulation of liposomes loaded with daunorubicin was observed in EGFR-positive A431 epidermoid carcinoma cells coexisting with a small fraction of EGFR-negative Balb-3T3 embryonic fibroblasts after pre-treatment with EGFR-targeted photodynamic therapy." (PMID 35808648, 2022). "Thus, in epidermoid carcinoma cells, tyrosine nitration altered the epidermal growth factor receptor (EGFR) activation through irreversible dimerisation." (PMID 36230630, 2022). "In addition, we ran an EGFR in-cell target engagement assay, measuring in-cell EGFR phosphorylation, using the human epidermoid carcinoma cell line A431." (PMID 35896603, 2022). "The diagnostic yield was higher in patients with adenocarcinoma (13.6%; 176 of 1,297) than in squamous cell carcinoma (5.9%; 21 of 354) (p = 0.001) and EGFR-mutant adenocarcinoma (17.5%; 85/487) than in EGFR wild-type adenocarcinoma (10.6%; 68/639) (p = 0.001)." (PMID 36457515, 2022). "In addition, smokers were more likely to have squamous cell carcinoma and KRAS mutation and less likely to have EGFR L858R, which were also confirmed after standardization of gender except KRAS mutations." (PMID 35061839, 2022). "The reduction of Dsg2 on the squamous cell carcinoma membrane increased the release of extracellular vesicles (EVs) containing EGFR and Src and that these EVs containing EGFR and Src can modulate the tumor microenvironment, a step critical for tumor progression." (PMID 32989241, 2021). "Thus, our data confirmed that both EGFR inhibitors and EGFR ligands can inhibit the growth of squamous carcinoma cell colonies, and together they can counterbalance each other and enhance proliferation instead." (PMID 33748471, 2021). "EGFR activation leads to increased anaerobic glycolysis in tumour cells, glucose depletion and accumulation of lactate in squamous cell carcinomas, meaning that tumour-infiltrating T cells, may have to compete for metabolic fuels." (PMID 33169187, 2021). "A431 is a human epidermoid carcinoma cell line that overexpresses the EGFR." (PMID 34126069, 2021). "Using the combination of pan-cytokeratin, EGFR, β-catenin, Ki67, and podoplanin, a candidate cancer stem cell marker in squamous cell carcinoma, the highly proliferating and less differentiated tumor cells at the periphery of the tumor islet can be distinguished." (PMID 33936105, 2021). "These multifunctional nanoparticles may have promising potential for targeted and effective therapy against EGFR-highexpressing cells of epidermoid carcinoma." (PMID 34400966, 2021). "Notably, tumour regressions were more profound and durable compared to afatinib (irreversible EGFR inhibitor) and cetuximab (anti-EGFR monoclonal antibody) in murine xenograft models of epidermoid carcinoma (A431) and HNSCC (FaDu)." (PMID 33923305, 2021).
squamous cell carcinoma (continued). "In addition to regulation of EGFR activity at the cell surface, E-cadherin downregulation leads to EGFR upregulation on mRNA level in cells from squamous cell carcinoma of the head and neck." (PMID 35127732, 2021). "Of the 22 excluded cases, 13 were due to unknown EGFR mutation status, 5 were due to less than 3 months of treatment or less than 3 months of follow-up, 2 due to ECOG score greater than 2, 1 due to squamous cell carcinoma, and 1 due to combined thyroid cancer." (PMID 34034713, 2021). "In addition, in squamous cell carcinomas including ESCC, EGFR activation is associated with depleted tumour infiltrating lymphocytes and resistance to immune checkpoint inhibition (ICI)." (PMID 33169187, 2021). "In phase I, the inclusion criteria allowed enrollment of EGFR-mutated patients, and 5 EGFR-mutated subjects and no subjects with squamous cell carcinoma were enrolled." (PMID 32803700, 2021). "On the other hand, in the phase II of our study, the inclusion criteria did not allow enrollment of EGFR-mutated patients; all subjects were EGFR wild type, and 4 subjects with squamous cell carcinoma were enrolled." (PMID 32803700, 2021). "Nimotuzumab is a monoclonal antibody against epidermal growth factor receptor which can be combined with chemotherapy and radiotherapy for the treatment of locally advanced unresectable squamous cell carcinoma of head-and-neck region and its role has already been established in India." (PMID 34104833, 2021). "We investigated whether human blood serum can affect squamous carcinoma cell growth and EGFR drug response." (PMID 33748471, 2021). "To test this hypothesis, we analyzed the effects of peripheral human blood sera obtained from seven healthy donors, on the growth and sensitivity to EGFR-targeted drugs of squamous carcinoma cell line A431." (PMID 33748471, 2021). "Regarding the histological type among the 49 patients receiving EGFR mutation tests, 42 were adenocarcinomas, 5 were squamous cell carcinomas, and 2 were not-otherwise-specified NSCLCs." (PMID 34696229, 2021). "Additionally, EGF addition to human epidermoid carcinoma A431 cells, which highly express the EGFR, resulted in increased levels of intracellular ROS36." (PMID 32661331, 2020). "Kim and colleagues showed that the coexpression of EGFR and COX-2 may be used as a potent risk factor to predict the poor survival of patients with squamous cell carcinoma of the uterine cervix." (PMID 33392068, 2020). "Second, to the best of our knowledge, ALK fusion and EGFR L858R mutations in separate squamous cell carcinoma and adenocarcinoma diagnosed at the same time has not been reported." (PMID 32727606, 2020). "Pathological transformation to squamous cell carcinoma after epidermal growth factor receptor (EGFR)-tyrosine kinase inhibitor treatment has been reported, but details of the transformation remain unclear." (PMID 31956415, 2020). "Less than 10% (56/579) of the patients had non-adenocarcinomas (mostly squamous cell carcinomas), of whom only 5 had EGFR mutations (3.1% of all EGFR mutated patients)." (PMID 32714871, 2020). "However, this is understandable, as the majority of EGFR mutations and ALK-positivity cases were found in adenocarcinomas, with an extremely low mutation rate in squamous cell carcinoma (< 5%)." (PMID 32690092, 2020). "For NSCLC, previous studies have shown that approximately 80% of patients with squamous cell carcinoma and 65% of patients with adenocarcinomas have overexpression of EGFR protein, and the overexpression state is an important factor leading to radiation resistance." (PMID 32563259, 2020). "PLSCR1 has also been reported to interact with EGFR in EGF-stimulated epidermoid carcinoma cells." (PMID 32292520, 2020).
squamous cell carcinoma (continued). "Both mimotopes elicited Abs capable of triggering (i) cellular and complement-dependent cytotoxic effects against EGFR-expressing cells, (ii) EGFR internalization, and (iii) dose-dependent inhibition of proliferation in the EGFR-overexpressing human squamous carcinoma cell line A431." (PMID 32075083, 2020). "In this study, one potential reason for worse PFS in the EGFR wild-type group may be the rate of squamous cell carcinoma pathology, which was 82% in this group." (PMID 33331920, 2020). "In the present study, we report a case of synchronous multiple primary lung cancer (MPLC) composed of two distinct pathological subtypes with epidermal growth factor receptor (EGFR) gene mutations L858R of the acinar adenocarcinoma subtype and EML4–ALK rearrangement of the squamous cell carcinoma." (PMID 32727606, 2020). "In squamous cell carcinomas, EGFR is activated by MET, contributing to tumorigenesis." (PMID 33204717, 2020). "In order to test if the function of CHP-1 in the EGFR signaling pathway is conserved in mammals, we inactivated the CHP-1 homolog CHORDC1 in human A431 epidermoid carcinoma cells, which express high levels of the wild-type EGFR and undergo a phenotypic switch in response to EGF stimulation." (PMID 32053105, 2020). "In addition, GM3 overexpression has been shown to be located on lipid rafts complexed with EGFR and caveolin-1 in human squamous carcinoma cells inhibiting EGFR activation." (PMID 31578452, 2019). "The over expression and/or mutation of EGFR tyrosine kinase has been observed in many human solid tumors, including non-small cell lung, breast, ovarian and squamous cell cancers, EGFR has been under intense investigation as a novel anticancer molecular target." (PMID 30096806, 2018). "The ensemble of molecular studies has provided the recognition of the main somatic genetic lesions occurring in the two main tumor subtypes: thus, EGFR and KRAS mutations and ALK-EML4 fusions mainly occur in adenocarcinomas, while DDR2, FGFR2 and NFE212 mainly occur in squamous cell carcinomas." (PMID 30060526, 2018). "Several anti-EGFR aptamers have been developed and demonstrated antitumor effect in various cancers (vulvar carcinoma, lung carcinoma, breast cancer, glioblastoma, and epidermoid carcinoma)." (PMID 29562664, 2018). "Among them, 2 patients with squamous cell carcinoma and the patient with adenocarcinoma were investigated, but they were negative for epidermal growth factor receptor mutation at both the initial and second surgeries." (PMID 30097033, 2018). "Moreover, carbon-EBRT combined with anti-EGFR based EndoRT was studied using 131I-Cetuximab in a prototypic EGFR amplified A431 human squamous cell carcinoma xenograft model." (PMID 30042828, 2018). "Herein we describe clinical remission of invasive, poorly differentiated squamous cell carcinoma of the pre-auricular region with external auditory canal involvement using cetuximab, an epidermal growth factor receptor (EGFR) antibody; and nivolumab, a programmed death receptor-1 (PD-1) antibody." (PMID 29320468, 2018). "Thus, the EGFR-mediated suppression of IFNγ/TNFα induced chemokine expression in squamous cell carcinoma cells from the head and neck primarily is mediated by both the MEK and JNK signaling pathways." (PMID 30192802, 2018). "Therefore, we investigated the feasibility of applying this method to mediastinal lymph node metastases in an epidermal growth factor receptor (EGFR)-positive squamous cell carcinoma of the lung." (PMID 29856819, 2018). "However, anti-EGFR therapy has proven efficacy in patients with the squamous cell carcinoma histology as well." (PMID 29731995, 2018). "We next examined the effect of EGFR-MBs in a murine squamous cell carcinoma model." (PMID 28938010, 2017). "Furthermore, amphiregulin facilitates G-protein-coupled receptor (GPCR)-mediated transactivation of EGFR signaling and was shown to induce cellular proliferation and motility in squamous cell carcinoma." (PMID 29254206, 2017).
squamous cell carcinoma (continued). "Over the last few years, the application of NIR-tPDT has been explored as a treatment option in several solid tumors; initially EGFR-targeting NIR-tPDT in vitro and in vivo experiments were performed using only the high EGFR-expressing epidermoid carcinoma cell line A431." (PMID 28415738, 2017). "Asian descent, female sex, adenocarcinoma histology and never-smoking status are established clinical characteristics that are associated with higher incidence of EGFR mutation, compared to non-Asian descent, male sex, squamous cell carcinoma and ever-smokers." (PMID 29232915, 2017). "In four squamous cell carcinoma patients with EGFR mutations, two had the T790M mutation without EGFR activating mutations, while the other two were positive for exon 19 deletion and L858R, respectively." (PMID 29290998, 2017). "In the TCGA dataset, a total of 408 NSCLC samples (230 adenocarcinomas and 178 squamous cell carcinomas) that had not been treated with chemotherapy, including EGFR-TKIs, were analyzed, and 30 samples had EGFR mutations in exons 18–21." (PMID 28424065, 2017). "We first performed far-Western blotting, a reverse-phase SH2 binding assay to quantify changes in the binding sites for multiple SH2 domains across the set of phosphoproteins in EGF-stimulated A431 cells, an EGFR-overexpressing squamous-cell carcinoma cell line." (PMID 27071344, 2016). "In this study, we assessed the prognostic value of EGFR expression in squamous cell carcinoma." (PMID 27438047, 2016). "Adenocarcinoma and squamous cell carcinoma histology each comprised 35 % of cases, and no EGFR mutations were detected." (PMID 27350261, 2016). "Therefore we used the EGF stimulated human squamous carcinoma cell line A431 with a high expression of EGFR." (PMID 27322232, 2016). "Moreover, even in squamous cell carcinoma patients who achieved a partial response by EGFR-TKI, the median PFS was shorter than patients with adenocarcinoma harboring EGFR mutations." (PMID 27072585, 2016). "To examine the ability of ZEGFR:2377 to detect different EGFR expression levels in tumors with varying characteristics, we used two models (A431 (epidermoid carcinoma) and FaDu (squamous cell carcinoma)) and, in one series, examined changes in tracer uptake with the growth of A431 tumors." (PMID 27388754, 2016). "Among non-adenocarcinoma patients, EGFR mutations were detected in 15 squamous cell carcinomas, 8 adenosquamous carcinomas 8 and 4 large cell lung carcinomas." (PMID 27072585, 2016). "Serum SCCA levels were not different between squamous cell carcinoma patients with or without EGFR mutations, nor did it have a relationship with DFS or OS." (PMID 27072585, 2016). "The percentage of mutated adenocarcinomas was 12.8% (92 out of 716 adenocarcinomas), whilst in all other histological types the percentage of EGFR mutations did not surpass 5% (9 out of 240 samples), and no mutation was detected in squamous cell carcinomas." (PMID 26208325, 2015). "Finally we tested A431 epidermoid carcinoma cells, which harbor Epidermal GrowthFactor Receptor (EGFR) overexpression." (PMID 25976978, 2015). "Third, the studies did not report the data of patients with EGFR mutations, EGFR wild-type, adenocarcinoma and squamous cell carcinoma." (PMID 26285137, 2015). "In the current study, we investigated the effect of resveratrol and its two 4′-methylthio-trans-stilbene derivatives (3-M-4′-MTS; S2) (3,5-DM-4′′-MTS; S5) on EGFR and Stat3 activation in human immortalized HaCaT keratinocytes and epidermoid carcinoma A431 cells." (PMID 25063218, 2014). "Two 4′-methylthio-trans-stilbene derivatives possessing one (3-M-4′-MTS; S2) and two (3,5-DM-4′-MTS; S5) methoxy groups were assessed, and immortalized human HaCaT keratinocytes and human epidermoid carcinoma A431 cells differing in EGFR constitutive expression were applied as an experimental model." (PMID 25063218, 2014).